OR10Q1 (olfactory receptor family 10 subfamily Q member 1)
Description:
Odorant receptor.
Synonyms: OR11-233
Tractability: Antibody: UniProt places it where antibodies can reach, with medium confidence; UniProt predicts a signal peptide or a membrane-spanning region; its Gene Ontology location is reachable by antibodies, with medium confidence.
Gene: Protein-coding gene on chromosome 11 (58,227,882 to 58,228,918, reverse strand). Ensembl gene ENSG00000180475.
Subcellular location: Cell membrane
Subcellular location (Human Protein Atlas): Mid piece
Pathways (Reactome):
Sensory Perception: Expression and translocation of olfactory receptors
Gene Ontology:
Molecular function: odorant binding; olfactory receptor activity; G protein-coupled receptor activity
Biological process: sensory perception of smell; detection of chemical stimulus involved in sensory perception of smell; G protein-coupled receptor signaling pathway
Cellular component: plasma membrane; membrane
Genetic constraint (gnomAD): Loss-of-function variants: 0 observed, 0.12 expected, observed/expected ratio (o/e) 0, 90% interval 0 to 1.89. That is too few expected variants to judge how well the gene tolerates losing a copy. Missense variants: 435 observed, 432.98 expected, observed/expected ratio (o/e) 1, 90% interval 0.93 to 1.09. Synonymous variants: 211 observed, 189.1 expected, observed/expected ratio (o/e) 1.12, 90% interval 1 to 1.25.
Homologues: Orthologues: chimpanzee OR10Q1 (97% identical), macaque OR10Q1 (92% identical), dog OR10Q1 (84% identical), mouse Or10q1 (82% identical), mouse Or10q1b (81% identical), dog OR10Q2 (81% identical), mouse Or10q12 (73% identical). Paralogues in human: OR10V1 (53% identical), OR10W1 (50% identical), OR5A1 (45% identical), OR9G4 (45% identical), OR5M10 (43% identical), OR5AU1 (42% identical), OR5M1 (42% identical), OR5A2 (42% identical), OR5AS1 (42% identical), OR5I1 (42% identical), OR5M11 (42% identical), OR9K2 (42% identical), and 84 more.